CDK6 (cyclin dependent kinase 6)
Diseases named in the same sentence as CDK6 in open-access papers (continued):
Sharing a sentence is not in itself a finding about the gene and the disease.
tumor (continued). "In these cancers, the tumor suppressive role of miR-145 is achieved, at least partially, through the regulation of cell cycle-related proteins such as CDK6, CDK2, and cyclin D1, and direct targeting of oncogenes, including N-RAS and VEGF-A." (PMID 35563814, 2022). "To date, at least 20 CDKs and 30 cyclins have been reported, and of these, emerging evidence suggests that CDK6 has a vital transcriptional role in tumor angiogenesis and thus represents a promising target for antitumor treatment." (PMID 35480115, 2022). "At the pan-cancer level, the effect of CDK6 on tumor immune cell infiltration in different tumors is very heterogeneous." (PMID 35480115, 2022). "It was reported that CKAP4 was minimally expressed in non-tumor cells, therefore, it was adopted as a biomarker for investigation of KB-C2 and KB-C2-k.o.cdk6 metastasis in the tissues of nude mice." (PMID 35459184, 2022). "High levels of tumor cell metastasis were detected in the liver, lung and spleen of KB-C2 tumor-bearing nude mice, and more tumor cells were distributed inside the organs, as compared with KB-C2-k.o.cdk6 tumor- bearing nude mice." (PMID 35459184, 2022). "In our study, we found that CDK6 expression was indeed higher in tumor tissues than in normal tissues." (PMID 35780240, 2022). "A comprehensive evaluation of the correlations between CDK6 and tumor immune checkpoint genes at the pan-cancer level shows that CDK6 is similar in its infiltration of tumor immune cells." (PMID 35480115, 2022). "The expression levels of proteins associated with the cell cycle (CDK4, CDK6 and cyclin D1), proliferation (Ki67 and PCNA) and the pathway (GSK-3β, p-GSK-3β, β-catenin) in tumor tissue samples were determined using western blotting." (PMID 34719320, 2022). "These tumours express high CDK6 protein levels, and their cell lines were noted to be highly sensitive to CDK6 knockdown, indicating that CDK4/6 inhibitors are good candidates for treatment." (PMID 36077812, 2022). "CDK6 overexpression has been found in several cancers, and tumor drug resistance increases when CDK6 expression is elevated." (PMID 35896848, 2022). "As a tumor suppressor, miR-211 inhibits cell proliferation and induces cell apoptosis by down-regulating cyclin D1 and CDK6 in OC to block cells in G0/G1 phase 36." (PMID 35912006, 2022). "All of the miRNAs- miR-137, miR-186-5p, miR-214-3p, miR-129-5p, miR-185, miR-107 and let-7 correlated with CDK6 expression in their respective tumor suppressive pathways." (PMID 36303933, 2022). "Dysregulated CDK6 promotes the senescence bypass during tumorigenesis and progression and its inhibition restores the senescence response in tumor cells." (PMID 36052073, 2022). "We downloaded CDK6 methylation data and found that CDK6 methylation was higher in tumor tissues than in normal samples and that CDK6 methylation was correlated with the expression of CDK6 mRNA in PCa." (PMID 35780240, 2022). "CDK6-related tumor immune infiltration analysis using the CIBERSORT and quanTIseq methods produced different results." (PMID 35480115, 2022). "Downregulation of CDK4/CDK6 in combination with p21 upregulation are major regulators of cell cycle arrest and important for tumor growth reduction." (PMID 35884996, 2022). "CDK6 was found to be regulated in multiple cases of tumor suppressing events between lung adenocarcinoma and NSCLC." (PMID 36303933, 2022). "CCND1 (cyclin D1) is one of the regulators of CDK kinases by forming complexes with CDK4 or CDK6 as a subunit, whose tumor-promoting role in the development of human cancers has been intensively investigated." (PMID 35365622, 2022). "SHR6390, a novel CDK4/CDK6 inhibitor, demonstrates high potency in in vitro antiproliferative action toward the spread of Rb-positive human tumor cells." (PMID 34361615, 2021). "In line, CDK6 has previously been reported to regulate tumor cell metabolism in a kinase-dependent manner." (PMID 34248938, 2021).
tumor (continued). "For example, several genes linked to RA credible SNPs in FLS were implicated in cell proliferation and tumor development (e.g., SPRED2, GRHL2, CDK6, RUNX1, and ZFP36L)." (PMID 34433485, 2021). "Aberrant expression of Cdk6 protein has been reported in many tumors suggesting that Cdk6 protein promotes tumor progression and contributes to chronic inflammation and neoplasia through NF-κB." (PMID 33865415, 2021). "Because this signaling impacts on the cell cycle, cyclin-D1/CDK4 and CDK6 function, autophagy and IR are involved in many human neoplasms." (PMID 34445095, 2021). "Tumor-associated genes on Chr9q such as FANCC, NTRK2, SYK, and NOTCH1 were amplified; amplification of BRAF, EZH2, MET, CDK6 and HGF located on Chr7 were also detected." (PMID 34895266, 2021). "Accumulating evidence revealed the involvement of CDK6 in cancer pathogenesis, where it functions as a promising tumor promoter." (PMID 34796112, 2021). "The tumor tissues were subjected to whole exome sequencing (WES) and four mutations with potential clinical significance were identified: CDKN2A deletion, CDK6 amplification, PIK3CA amplification, and KRAS G12V mutation." (PMID 34327143, 2021). "A negative correlation was observed between miR-576 and CDK6 expressions (r = −0.75, P < 0.001), whereas a positive correlation was observed between FTO and CDK6 expressions (r = 0.71, P < 0.001) in 20 tumour tissues." (PMID 34725345, 2021). "Luciferase reporter assay was performed to identify the correlations among miR-29c, HOXA-AS3 and 3' UTR of CDK6.The ability of cell proliferation was assessed by cell counting and subcutaneous tumor growth assay." (PMID 34659534, 2021). "The IHC of subcutaneous xenograft tumours showed that the positive rate of CDK6 and Ki-67 increased significantly in the FTO-overexpression group and decreased significantly in the FTO-knockdown group." (PMID 34725345, 2021). "The expression of CDK6 in the tumours injected with FTO-overexpressing cells increased significantly compared to those injected with control cells (NC), while opposite results were obtained in the FTO-knockdown group." (PMID 34725345, 2021). "In comparison with normal control, the expression of CDK6 was notably upregulated in tumor samples compared with normal control." (PMID 34796112, 2021). "Inhibition of CDK4 and CDK6 can prevent cell cycle progression, prevent tumor growth and promote senescence." (PMID 34395246, 2021). "Furthermore, miR-34a encapsulated in chitosan/PLGA nanoparticles inhibited tumor growth in murine xenograft models of human multiple myeloma disease since this miRNA directly downregulates proteins associated with tumor development, i.e., Bcl-2, Notch 1, and CDK6." (PMID 35011442, 2021). "In this study, we used CRISPR technology to suppress lncRNA expression and provided several evidences supporting a critical role for lncRNA HOXA-AS3 in tumor-promoting effects by targeting miR-29c/CDK6 axis." (PMID 34659534, 2021). "Our finding of RB1 deletions in 34% of tumours with CDKN2A deletion makes responses to CDK4/CDK6 antagonists less likely and underpins our finding that the CDK4/CDK6 inhibitor Palbociclib had marginal effects on primary cell survival." (PMID 34580349, 2021). "Instead, comparable levels between tumours and normal mammary glands were found for Cdk3, Cdk5, and Cdk6." (PMID 34646365, 2021). "The crosstalk between the PI3K-mTOR and CDK4/CDK6 paths provides a strong rationale in combining both routes to inhibit tumor growth." (PMID 34361615, 2021). "Last but not least, evidences accumulated in the last few years highlighted a role for CDK4 and CDK6 inhibition in triggering anti-tumor immunity." (PMID 34204543, 2021). "CDK6-regulated genes include tumor-suppressors, tumor-promoters and inflammatory cytokines, adding complexity to the role of CDK6 during homeostasis and tumorigenesis." (PMID 34248938, 2021).
tumor (continued). "Recent studies have also revealed that CDK6 is regulated by upstream noncoding RNA, and it indirectly affects tumor lymph node metastasis and other biological behaviors." (PMID 34152098, 2021). "CDK6 is a well-known important cell cycle regulator which plays a critical role in tumor progression." (PMID 32584787, 2020). "A recent report found miR-29b, which upregulates CDK6, to be a tumor suppressor via targeting multiple important oncogenic pathways." (PMID 33597968, 2020). "CDK4/CDK6 inhibitor palbociclib reduces tumor growth by reducing retinoblastoma (RB) protein phosphorylation and cell cycle arrest, which induces G1/S phase transition." (PMID 32508030, 2020). "Hsa_circ_000984 acts as a competing endogenous RNA (ceRNA) by competitively binding to miR-106b and effectively upregulating CDK6 expression, thereby inducing a series of malignant phenotypes of tumor cells." (PMID 32158464, 2020). "Aberrant expression of PCAT-1 in the tumor microenvironment negative regulates p27/CDK6 by inducing G0/G1 cell cycle arrest and AMPK augmentation, contributing to a tumor-favoring metabolic status." (PMID 32754302, 2020). "Arsenic trioxide causes tumour cell differentiation, triggers cell apoptosis and induces G1 and/or G2-M phase arrest via down-regulation of CDK2, CDK6, cyclin D1, Cyclin E, Cyclin A and Cdc2 kinase." (PMID 32002123, 2020). "On the one hand, the kinase-dependent function of CDK6 in the cell cycle machinery is exploited by rapidly proliferating tumor cells to rush through the cell cycle." (PMID 33255177, 2020). "Among these genes, we found that IGF1R and CDK6 that are involved in regulation of cancer cell proliferation and tumor growth." (PMID 33219221, 2020). "It was found to be downregulated in patient tumor samples, where miR-124 and Cdk6 expression levels were inversely correlated." (PMID 32528946, 2020). "This combination inhibits RB hyperphosphorylation by inhibiting the cyclin D1/CDK4/CDK6 complex, inducing cell cycle arrest and inhibiting tumor growth." (PMID 32508030, 2020). "Other studies showed that CDK4 and CDK6 played a role in anti-apoptosis via inhibiting the activation of Caspase 3 in tumor cells." (PMID 32860670, 2020). "High phosphorylation of Rb by activating Cyclin D-CDK4 /CDK6 complex was an important reason for the rapid proliferation in GBM cells and the proliferation capacity of tumor cells was significantly reduced after the intervention of CDK4/CDK6 inhibitors." (PMID 32860670, 2020). "We also learned that when CDK6 expression is high, the tumor is often accompanied by the activation of the Wnt /β‐catenin pathway, and palbociclib reduces the Ser9‐GSK3β phosphorylation and ultimately induces β‐catenin degradation." (PMID 32508030, 2020). "Based on panel sequencing with a CDK6 amplification and decision of our interdisciplinary tumor board, abemaciclib in combination with temozolomide was initiated in the fourth relapse." (PMID 32758285, 2020). "Upregulation of circ_0072995 effectively enhanced cell proliferation and invasion in vitro and promoted tumor growth in vivo by way of targeting the miR-147a/CDK6 axis." (PMID 32877369, 2020). "On the other hand, prolonged treatment eventually provokes resistance, which has been attributed to the loss of the Rb tumor-suppressor or cyclin D1, activation of CDK2, cyclin E1 and amplification of CDK6." (PMID 33255177, 2020). "In a TMZ-R patient-derived xenograft mouse model, the combination of TMZ and palbociclib delayed tumor growth, and tissue analysis by RT-PCR showed the lowest level of β-catenin, Sox2, CDK6, and lncSNHG15." (PMID 32178454, 2020). "The gene deletion of CDKN2A and CDKN2B in tumor cells resulted in high activities of CDK4/CDK6, and made cells transit from G1 phase to S phase leading to rapid cell proliferation." (PMID 32860670, 2020). "In this context, it is worth mentioning a recent study showing that the specific CDK4/CDK6 inhibitor Abemaciclib promoted anti-tumor immunity through ICD induction." (PMID 32455811, 2020).
tumor (continued). "Cyclin-dependent kinase, CDK6, is a driving factor for cell proliferation and can bind D cell cycle protein 3 to promote tumor cell apoptosis." (PMID 32153632, 2020). "Among them, BCL2 and CDK6 were found downregulated at mRNA levels and then confirmed at protein levels in primary patient-derived cancer cells and tumor lysates from mice upon BORA depletion." (PMID 32268485, 2020). "In GBM samples, tumor-suppressive miR-627 is significantly downregulated, while lncSNHG15 and CDK6 are overexpressed." (PMID 32178454, 2020). "Of note, previous studies have shown that STAT1 activation can promote miR-29 transcription and that miR-29 can decrease tumor cell proliferation by downregulating CDK6, corroborating our western blot data." (PMID 31382461, 2019). "In 39-Mseq cohort, 8 out of 39 patients carried focal amplifications of CDK6; of which, amplifications in 7 patients were ubiquitous, highlighting the importance of CDK6 as a potential druggable target for all tumor cells (TCs) for CDK6-amplified patients." (PMID 30975989, 2019). "shRNA knockdown of either CDK4 or CDK6 significantly reduces cell proliferation and impedes their migratory capacity in vitro, which translates into a strong inhibition of tumor growth in xenotransplantation experiments." (PMID 30858922, 2019). "Subsequently, using bioinformatics tool, a potential mechanistic route for SNHG15 to promote GBM tumorigenesis was by inhibiting tumor suppressor, miR-627-5p which leads to activation of CDK6." (PMID 31462285, 2019). "Overall, our results indicate a tumor-suppressive role of miR-1296-5p through the translational repression of oncogenic CDK6 and EGFR in GC." (PMID 30530570, 2019). "Here, we test the potential of using CDK6 inhibitor, palbociclib for the treatment of TMZ resistant GBM cells and associated effects on the tumor microenvironment." (PMID 31462285, 2019). "In contrast to PD0332991 treatment which allowed tumor formation in a delayed manner, knockdown of CDK4 or CDK6 resulted in the inability of cells to form any tumor." (PMID 30858922, 2019). "Specifically, a positive correlation between urine GOAT levels and the expression levels (in the tumor pieces) of CDK6, EGF, EZH2 and NF-KB was found in patients with PCa." (PMID 31766715, 2019). "To independently assess the role of Cdk6 we generated Cdk6 knockout tumour cell clones using CRISPR/Cas9 gene editing." (PMID 30926782, 2019). "Unexpectedly, we identified a pro-survival function of FOXO3a in tumor cells via an upregulation of CDK6 gene expression." (PMID 30518851, 2018). "It is a well-established tumor suppressor gene which can form a complex with CDK4 or CDK6 and prevents the activation of the cyclin dependent kinase to inhibit cell cycle progression." (PMID 30266084, 2018). "The detection of serum circ-ZEB1.33 can reflect the CDK6 level in the tumor tissue, so we think serum circ-ZEB1.33 is a potentially valuable biomarker for HCC diagnosis." (PMID 30123094, 2018). "MiR-124 exerts a tumour suppressor effect by targeting cyclin-dependent kinase 6, and epigenetic silencing of miR-124 leads to CDK6 activation and Rb phosphorylation." (PMID 30258192, 2018). "More recently, CDK6 has also been shown to have a transcriptional role in tumour angiogenesis, being a part of a transcription complex that induces the expression of the tumour suppressor p16INK4a and the pro-angiogenic factor VEGF-A." (PMID 30517191, 2018). "A decrease by 90% in the cyclin D1, CDK4 and CDK6 levels was observed in the erufosine treated tumor samples." (PMID 29464035, 2018). "CDK family members, such as CDK2, CDK4, and CDK6, play a key role in the cell-cycle control of tumor cells." (PMID 29370087, 2018). "The most significant association was obtained with the Cyclin Dependent Kinase 6 (CDK6) gene, whose overexpression is associated with short time before tumor relapse and death of patients." (PMID 29283884, 2017).
tumor (continued). "As is well-known, CDK protein family (including CDK6) is the core molecular in the tumor cell cycle regulation, accompanying with cyclin and cyclin-dependent-kinase inhibitor (CKI)." (PMID 29179477, 2017). "GAS5 is a multi-functional lncRNA in CRC cells as it induces cell cycle arrest and tumor cell apoptosis by enhancing the G1 cell cycle through the cyclin-dependent kinase 6 (CDK6) pathway." (PMID 28392501, 2017). "The functional study revealed that miR-124 targeted CDK6 and inhibited cell proliferation in vitro, which suggests its role as a tumour suppressor." (PMID 28861128, 2017). "miR-449a has been reported to suppress tumor cell proliferation/growth and survival by targeting CDK6, CDC25A, Sirt1, HDAC1, cyclinD1, WISP2, and c-Met." (PMID 29254139, 2017). "p15 and p16 inhibits CDK4 and CDK6, therefore p15 and p16 act as tumor suppressors and lead to cell cycle arrest in the late G1 phase." (PMID 28484518, 2017). "As control, correlation of potential reference gene and suspected tumor markers (CDK6 and TYMS) was performed revealing very low R2-values, as expected." (PMID 27802291, 2016). "A tumor suppressor miRNA, miR-34a-5p, targeted several critical cancer genes, including CDK6, CCND1, CCNE2, E2F3 in the cell cycle pathway and VEGFA in the angiogenesis pathway." (PMID 27329603, 2016). "For example, CDK6 plays critical roles in regulating the progression of cell cycle and have been recently demonstrated to have a transcriptional role in tumor angiogenesis." (PMID 27580177, 2016). "We detected specific expression for EGFR, MET and CDK6 proteins in tumor cells of all tumor samples studied by IHC." (PMID 27329726, 2016). "Immunohistochemistry and Western blot also consistently showed that the expression of E2F2, CDK3, and CDK6 in miR-214-overexpressing cell-line tumor models were lower than those in the vector-control tumors." (PMID 26498144, 2016). "As control, the coefficient of determination was also calculated for the reference genes and tumor markers CDK6 and TYMS and showed considerably low correlations between them." (PMID 27802291, 2016). "As expected, there was a down regulation of cellular proliferation molecules CDK1, CDK2, CDK4, CDK6, Cyclin D1, Cyclin E and Cyclin B1 and upregulation of p16 and p21 in the xenograft tumor tissues by IHC." (PMID 26590805, 2015). "For instance, CDK6 overexpression has been reported to have an anti-proliferative effect in vivo resulting in the delay of tumor formation." (PMID 25914884, 2015). "Treatment of mice with honokiol resulted in a marked decrease in the expressions of cyclin D1 and cyclin D2 and reduced expressions of Cdk4 and Cdk6 in tumor samples obtained from honokiol-treated mice compared to tumor samples from control mice." (PMID 26020804, 2015). "The Western blot employing antibodies to Cdk6 demonstrates that this gene is amplified and overexpressed in all 10 tumor samples compared with normal thymic T cells." (PMID 25452272, 2014). "To test the importance for tumor growth and metastasis of these genes we introduced inducible cDNAs of CDK6, CDK14 and Fzd6 alone or in combination into the parental ES cell line of the β-Catenin driven model, 91C5, and generated chimeric mice." (PMID 25162504, 2014). "We therefore measured the effects of embelin on the expression of cell cycle proteins (Cyclin D1, CDK-2, and CDK-6), and Bcl-2 family members (Bcl-2, and Bax) in tumor tissues by Western blot analysis and immunohistochemistry." (PMID 24694877, 2014). "For example, CDKN1B directly binds and inhibits CDK6 (known to have a tumor suppressive role), whose underexpression implies a poor prognosis." (PMID 25425654, 2014).